NQO1 (NAD(P)H quinone dehydrogenase 1)
Diseases named in the same sentence as NQO1 in open-access papers (continued):
Sharing a sentence is not in itself a finding about the gene and the disease.
colitis (24 papers, 2017 to 2025). Inflammation of the colon. "Previous results in a model of acute colitis associated increased lipid peroxidation (MDA) with decreased levels of NQO-1 and SOD." (PMID 32998266, 2020). "As a metabolite of CGA, CA could effectively ameliorate DSS-induced colitis mice by increasing mRNA expression levels of HO-1, NQO1, and Nrf-2 potentially associated with Nrf-2 pathway in this study." (PMID 34867926, 2021). "Puerarin elevates the expression and protein content of Nrf2, as well as antioxidant enzymes such as CAT, GSH, SOD, HO-1, and NQO1, in mice with sodium glucan sulfate-induced colitis, indicating apparent oxidative protective effects." (PMID 36432411, 2022). "It was found that RUS ameliorates murine colitis through activation of the Nrf2/NQO1 pathway which was presented as a decrease in inflammation score and downregulated levels of cytokine and chemokine synthesis, as well as increased intestinal permeability." (PMID 35308175, 2022). "In contrast, supplementation with the same dose of FECs, especially ISO and SFN, significantly improved DSS-induced colitis in mice by increasing the mRNA and protein expression levels of Nrf2, NQO1, and HO-1." (PMID 36552614, 2022). "The larger the logP value, the higher the expression of Nrf2, NQO1, and HO-1, and the higher the mitigative effect in colitis." (PMID 36552614, 2022). "Our research showed that Forsythia suspensa extract can increase the protein and gene expression levels of Keap1, HO-1, Nrf2 and NQO1 in mice with colitis." (PMID 35326124, 2022). "Analysis of NRF2 target genes involved in ROS detoxification (Nqo1, Gsta2) and heme/iron metabolism (Hmox1) at the apex of acute murine colitis shows a more nuanced picture with all three genes being differentially affected by Nox4 deficiency." (PMID 33059312, 2020). "Similar protective effects, through activation of Nrf2 signaling in DSS-induced colitis in mice, were described for luteolin, oligonol, and sinomenine, which were able to activate also the Nrf2-downstream partner NQO-1." (PMID 31434263, 2019). "In the correlation analysis, logP value was found to be the main influencing factor for FECS to activate Nrf2 and mediated the expression of downstream proteins (NQO1, HO-1), which explains why FECs with low logP value have a poor effect in ameliorating colitis." (PMID 36552614, 2022). "Mice with DSS-induced colitis exhibited substantially decreased expression of Nrf2, HO-1, and NQO-1 and increased expression of Keap1 in colon tissues; however, the expression of these proteins was significantly improved only after 25 μM H2O2-preconditioned MSC-CM treatment." (PMID 36456585, 2022). "Moreover, Western Blot analysis showed that the total expression of HO-1 and NQO-1 in colon tissues of DSS-induced colitis mice were promoted by FA-97, as well as the nuclear Nrf2 level was also increased by FA-97 treatment." (PMID 31969881, 2019). "Furthermore, liver IHC staining revealed that colitis caused oxidative stress in the liver, which BBR-EVO may significantly relieve by stimulating the expression of the Nrf2/NQO1 protein." (PMID 39296302, 2024). "Therefore, we investigated the protein expression of Nrf2, HO-1, and NQO1 to determine whether OJE administration affects oxidative stress in mice with DSS-induced colitis." (PMID 36552637, 2022). "On the other side, DSS-induced colitis in COX-2−/− KO mice was less severe compared to WT control mice, showing a decrease of heme oxygenase-1 (HO-1) and increase of NADPH quinone oxidoreductase-1 (NQO-1), demonstrating the tight association between inflammation and the antioxidant system." (PMID 31434263, 2019). "GSH-Px activity and Nrf-2, HO-1, and NQO-1 mRNA and protein levels were upregulated in liver tissues, thereby effectively alleviating DSS-induced liver injury secondary to colitis." (PMID 39202931, 2024). "Our results showed that significant inhibition of Nrf2 and its downstream genes NQO1 and HO-1 was observed in DSS-induced colitis mice." (PMID 36552614, 2022).
colitis (continued). "Compared with the CON group, the mRNA and protein expression levels of Nrf2, NQO1, and HO-1 were significantly reduced in the colon tissue of DSS-induced colitis mice." (PMID 36552614, 2022). "The protein expression of Nrf2, HO-1, and NQO1, which are phase 2 antioxidant enzymes, significantly (p < 0.001) decreased in DSS-induced colitis, and was significantly (p < 0.05) increased by OJE administration." (PMID 36552637, 2022). "Western immunoblotting revealed that, while both RSV and C33 maintained high expression levels of Ho-1 in WT colitis mice, C33 induced higher expression of Gstm1, AKR1B8, and Nqo1 proteins than RSV (lanes 2 and 3)." (PMID 31885813, 2019). "In studies involving murine colitis models, the activation of Nrf2 improved epithelial integrity and reduced IBD severity by upregulating antioxidant enzymes such as NAD(P)H quinone oxidoreductase 1 (NQO1), heme oxygenase-1 (HO-1), and glutathione S-transferase (GST)." (PMID 40563329, 2025). "However, the combination therapy of 5-ASA with ZnONPs induced relatively the highest increased expression of Nrf2 and NQO-1, demonstrating that the combination therapy of 5-ASA with ZnONPs attenuates oxidative stress in colitis mice by modulating Nrf2 signaling pathways." (PMID 28233796, 2017). "In addition, ZnONP treatment could induce upstream regulation of Nrf2 and NQO-1, which are the proteins representative antioxidant and cytoprotective factors involved in colitis and cancer chemoprevention." (PMID 28233796, 2017).
glioma (24 papers, 2012 to 2025). A benign or malignant brain and spinal cord tumor that arises from glial cells (astrocytes, oligodendrocytes, ependymal cells). "The survival analysis showed that high level of NQO1 is associated with the low survival rates of glioma patients." (PMID 36349191, 2022). "Altogether, these data are consistent with the idea that the loss of NSUN5 in glioma cells restricts general protein synthesis while activating the selective synthesis of specific stress-related proteins such as NQO1." (PMID 31428936, 2019). "Besides, NQO1 mRNA expression levels were positively associated with the age of patients in the pan-kidney cohort, brain lower grade glioma, and glioma." (PMID 37583897, 2023). "The finding that NSUN5 epigenetic silencing was associated with NQO1 overexpression prompted us to study whether these glioma cells might be more vulnerable to compounds targeting this particular stress-related protein." (PMID 31428936, 2019). "The search for potential plant-originating molecules was performed using SCOPUS and ScienceDirect base with key words that included “NQO1”, “glioma”, “glioblastoma”, and “plant” “downregulated”, yielding roughly 200 publications." (PMID 40002465, 2025). "The growth-inhibitory effects of plumbagin are modulated by NQO1; suppression (via dicumarol) or elimination (via NQO1 knockdown) of NQO1 reduces plumbagin-induced ferroptosis in glioma cells." (PMID 39534872, 2024). "Plumbagin increased NAD(P)H quinone dehydrogenase 1 (NQO1) activity and decreased xCT expression, resulting in NQO1-dependent glioma cell death." (PMID 39021832, 2024). "Targeting the NQO1-mediated pathway of ferroptosis represents another novel therapeutic strategy for the treatment of glioma." (PMID 38167027, 2024). "In a study on glioma, it was shown that CEBPB is associated with the expression of NQO1 and GSTP1 and can regulate the expression of antioxidant enzymes to regulate oxidative stress and mediate tumor growth in the brain." (PMID 38710698, 2024). "In glioma and acute myeloid leukemia, NQO1 mRNA levels were negatively correlated with CD4 T cells while positively correlated with CD8 T cells." (PMID 37583897, 2023). "The Cox regression analysis showed that overexpression of the NQO1 gene was related to poor OS in Glioma, uveal melanoma, head and neck squamous cell carcinoma, kidney renal papillary cell carcinoma, and adrenocortical carcinoma." (PMID 37583897, 2023). "Silencing of NQO1 reduced the luciferase activity of psiCHECK2-SERPINA1-3′UTR in primary glioma cells." (PMID 36349191, 2022). "pcDNA-SERPINA1 rescued the effects of sh-NQO1 in the primary glioma cell proliferation and apoptosis." (PMID 36349191, 2022). "In conclusion, our work demonstrates that in glioma cells, NQO1 enhances the translation of SERPINA1 mRNA by binding with 3′UTR and thus promotes the function of SERPINA1 by suppressing apoptosis and enhancing the proliferation." (PMID 36349191, 2022). "NSUN5 methylation-mediated overexpression of NQO1 can also constitute a therapeutic opportunity in these gliomas, because they become more sensitive to ROS-induced death upon the use NQO1-bioactivatable molecules." (PMID 31428936, 2019). "NQO1 is elevated in gliomas, and it prevents oxidative-stress-mediated glioma cell death." (PMID 40847302, 2025). "Additionally, NSUN5 inactivation sensitises gliomas to NQO1‐targeted treatments and is a marker of long‐term survival in glioma patients, highlighting its significance in cancer's epitranscriptomic regulation." (PMID 38797935, 2024). "This study suggested that NQO1 may have similar effects on other target mRNAs and brings novel solution of antitumor treatments for glioma in the future work." (PMID 36349191, 2022). "The epigenetic deletion of NSUN5 in glioma downregulates rRNA methylation levels and subsequently increases growth factor translation, making glioma cells resistant to the stress-related enzyme NAD(P)H quinone dehydrogenase 1 sensitive." (PMID 36360287, 2022).
glioma (continued). "Previous studies showed that NQO1 increases glioma cell proliferation." (PMID 36349191, 2022). "SERPINA1 and NQO1 promoted glioma cell proliferation and suppressed cell apoptosis." (PMID 36349191, 2022). "In this study, we explored the functions of SERPINA1 in glioma tumorigenesis in vitro and then investigated whether NQO1 affects the protein expression of SERPINA1 and its mRNA level." (PMID 36349191, 2022). "The colony formation ability of glioma cells was suppressed by sh-NQO1 and enhanced by pcDNA-NQO1." (PMID 36349191, 2022). "Epigenetic loss of NSUN5 expression in gliomas leads to rRNA cytosine hypomethylation and to increased translation of survival factors, rendering glioma cells sensitive to substrates of the stress-related enzyme NAD(P)H quinone dehydrogenase 1 (NQO1)." (PMID 33461542, 2021). "Thus, the occurrence of NSUN5 methylation pinpoints glioma cells that are more sensitive to the cytotoxic effect of NQO1 substrates." (PMID 31428936, 2019). "Interestingly, NSUN5 epigenetic inactivation also renders these gliomas sensitive to bioactivatable substrates of the stress-related enzyme NQO1." (PMID 31428936, 2019). "Furthermore, by using four glioma cell lines (U251, T98G, LN-229, and A172), it has been shown that the interplay between NQO1 and the anti-oncogenic miR-1321 with the oncogene serpin family A member 1 has been shown to impact the proliferation and apoptosis of glioma cells." (PMID 38167027, 2024). "Moreover, SERPINA1 rescued the effects of sh-NQO1 in glioma cell malignant phenotypes." (PMID 36349191, 2022). "We made a hypothesis that NQO1 binds to SERPINA1 to play an oncogenic role in glioma cells." (PMID 36349191, 2022). "Especially, in silico analysis of glioma tissues of the multidimensional data set from TCGA revealed that CD147 are broadly positive associated with Nrf2 target genes regulating redox homeostasis, including NQO-1, HO-1, GSTK-1, and GSS, which further confirmed the CD147 regulation of Nrf2." (PMID 34421346, 2021). "Most significantly, we have shown that NSUN5 inactivation is a likely pathway used by glioma cells to overcome hostile stress conditions by restraining high energy-consuming global protein synthesis while stimulating the translation of adaptive proteins such as NQO1." (PMID 31428936, 2019). "Thus, NQO1 inhibitors might provide innovative pharmacological treatment strategy for therapeutic intervention to the most malignant EGFR amplified gliomas." (PMID 30595797, 2018). "Recent findings suggest that 29 restrains glioma development by targeting NQO1/GPX4-mediated ferroptosis, positioning it as a prospective ferroptosis inducer or glioma therapy." (PMID 40076568, 2025). "Targeting NQO1/GPX4-mediated ferroptosis by plumbagin suppresses in vitro and in vivo glioma growth." (PMID 39193375, 2024). "NQO1 binds with SERPINA1 mRNA and significantly increases its translation, thus boosting glioma tumorigenesis." (PMID 36349191, 2022). "However, the property of the binding of NQO1 to SERPINA1 in glioma cells remains unknown." (PMID 36349191, 2022). "Influences of NQO1, SERPINA1, and miR-1321 on the proliferation and apoptosis of glioma cells were assessed." (PMID 36349191, 2022). "In the present work, we confirmed that NQO1 functions as an RNA-binding protein (RBP) that binds with SERPINA1 mRNA and enhances its translation, facilitating the proliferation of glioma cells by reducing the apoptosis." (PMID 36349191, 2022). "We examined 16 single nucleotide polymorphisms (SNPs) of 9 antioxidant genes (GPX1, CAT, PON1, NQO1, SOD2/MnSOD, SOD3, and NOS1*2*3) in 384 glioma and 384 control cases in a Chinese hospital-based case–control study." (PMID 23259684, 2012). "Studies have shown that nicotinamide adenine dinucleotide phosphate quinone dehydrogenase 1 (NQO1) can promote the proliferation of glioblastoma multiforme cells and enhance the expression of SERPINA1, but its effects on glioma cells remain unknown." (PMID 36349191, 2022).
glioma (continued). "In conclusion, our findings showed that oncogene NQO1 and antioncogene miR-1321 bind to oncogene SERPINA1 to affect proliferation and apoptosis of glioma cells, which can bring new solution of antitumor treatments for glioma in the future." (PMID 36349191, 2022). "First, we demonstrated by western-blot analyses that the three studied glioma cell lines with NSUN5 hypermethylation (LN229, A172, and KS-1) showed high levels of NQO1, whereas minimal expression of NQO1 was observed in the three NSUN5 unmethylated cell lines (DBTRG-05MG, MO59 J, and CAS-1)." (PMID 31428936, 2019). "Reported in C6 glioma cells (astrocyte-like cell lines) and primary astrocytes with mixed glial cells, IS-induced activation of NF-kB, ROS, and pro-inflammatory cytokine production, and downregulation of cell-protective factors such as NRF-2, HO-1, or NQO1." (PMID 30764571, 2019). "Furthermore, we extended these assays to NSUN5 methylated LN229 glioma cells, where we have exogenously restored NSUN5 activity and thus depleted the NQO1 protein." (PMID 31428936, 2019). "Considering the pro-proliferative and anti-apoptotic effects of SERPINA1 in glioma, we had the hypothesis that by upregulating the expression of SERPINA1, NQO1 would enhance the proliferation of glioma cells and suppress apoptosis, and such hypothesis was confirmed by the rescue assays." (PMID 36349191, 2022). "sh-NQO1 did not affect SERPINA1 mRNA but decreased its protein expression in primary glioma cells." (PMID 36349191, 2022). "Modulating NQO1 levels can potentially induce anticancer effects through a non-apoptotic necrosis mechanism in U87MG and U251 glioma cells." (PMID 38167027, 2024).
glioblastoma (22 papers, 2013 to 2025). The most malignant astrocytic tumor (WHO grade IV). "It has been shown that NQO1 knockdown enhances ROS production and diminishes cell proliferation, but its overexpression increases proliferation in glioblastoma cells." (PMID 41300449, 2025). "The effect of the ROS retractor C/EBPβ on NQO1 expression in GBM has been evaluated in human glioblastoma cell lines and within an in vivo xenograft animal model." (PMID 38167027, 2024). "NQO1 is overexpressed in many tumors, including glioblastoma, inhibiting oxidative stress and preventing cancer cell death." (PMID 37370678, 2023). "In a glioblastoma study, the knockdown of NQO1 augmented ROS and diminished cell proliferation, whereas the overexpression of NQO1 attenuated ROS and increased cell proliferation in glioblastoma cells." (PMID 36290622, 2022). "The orthologue of the NADPH‐dependent quinone oxidoreductase (NQO1) in humans is over‐expressed in glioblastomas along with HsGSTP1." (PMID 29575327, 2018). "Moreover, Chr-A reduced NADPH levels, further increased the accumulation of ROS and intracellular H2O2 and downregulated antioxidant proteins, including Nrf-2, HO-1 and NQO-1, to trigger oxidative stress and thus curb glioblastoma progression." (PMID 39330272, 2024). "Our results also showed that Chr-A could increase the accumulation of ROS and intracellular H2O2 and downregulate the expression of antioxidant proteins including Nrf-2, HO-1 and NQO-1 to trigger oxidative stress and thus curb glioblastoma progression." (PMID 39330272, 2024). "In Glioblastoma multiforme, NQO1 mRNA expression was highest in mesenchymal and neural." (PMID 37583897, 2023). "SERPINA1 expression had positive correlation with NQO1 expression in glioblastoma." (PMID 36349191, 2022). "It has been reported that NQO1 knockout could inhibit the proliferation of glioblastoma cells, while overexpression promoted cell proliferation." (PMID 33841805, 2021). "C/EBPβ is a crucial transcription factor that responds to ROS and regulates the expression of NQO1 and GSTP1, which help neutralize ROS in glioblastoma cells." (PMID 41009025, 2025). "Kecheng Lei shows that MNPC, a small molecule NQO1 and GSTP1 dual inhibitor, can reduce ROS reaction via inhibiting both NADPH quinone oxidoreductase 1 (NQO1) and GSTP1, leading to apoptosis and mitigated glioblastoma (GBM) cell proliferation." (PMID 34238333, 2021). "Recently, we reported that NQO1 acts as a downstream target of PTEN in glioblastoma cells, promoting GBM cell proliferation and suppressing ROS." (PMID 33087132, 2020). "In the current study, we provide innovative evidence demonstrating that NQO1 acts as a downstream target of PTEN in glioblastoma cells, promoting GBM cell proliferation and suppressing ROS." (PMID 30595797, 2018).